CTLA4 (cytotoxic T-lymphocyte associated protein 4)
Diseases named in the same sentence as CTLA4 in open-access papers (continued):
Sharing a sentence is not in itself a finding about the gene and the disease.
hypophysitis (continued). "First, ICI-related pituitary hypophysitis is mainly reported to be secondary to CTLA-4 inhibitors such as ipilimumab, and the use of only one patient on a specific ICI in our cohort may have limited the identification of hypophysitis." (PMID 39695571, 2024). "Conversely, in this cohort, we did not record any hypophysitis, confirming that this life-threatening event, in contrast with the evidence observed with CTLA-4 blockade, is rare during PD-1 inhibitors treatment." (PMID 38683497, 2024). "Hypophysitis only occurred with CTLA-4 inhibitor-based therapy, but not in CPI therapies without (p = 0.007)." (PMID 37271776, 2023). "The probability of hypophysitis in conjunction with immune checkpoint inhibitor use is as follows: combination therapy (nivolumab + ipilimumab), 6.4% and 3.2%; CTLA-4 inhibitors, 0.4%; and PD-1 inhibitors, PD-L1 inhibitors, and CTLA-4 inhibitors, < 0.1%." (PMID 36913010, 2023). "A possible explanation is the physiological CTLA-4 expression in normal pituitary tissue, which might support the binding of CTLA-4 antibodies and result in hypophysitis." (PMID 37271776, 2023). "Hypophysitis has been seen in patients treated with anti-CTLA-4 antibodies and may develop from the antibodies binding to CTLA-4 in the pituitary." (PMID 36140312, 2022). "The highest incidence of hypophysitis on monotherapy is noted with anti-CTLA-4 therapy with ipilimumab rather than with tremelimumab, although hypophysitis can also develop during PD-1 block." (PMID 36614041, 2022). "A meta-analysis reported that the incidence of hypophysitis was higher with anti-CTLA-4 as compared to anti-PD-1 therapy, which may be related to pituitary expression of CTLA-4." (PMID 35681667, 2022). "Hypophysitis is an irAE that commonly presents following CTLA-4 antibody blockage but not with PD-1 inhibitor treatment." (PMID 34094910, 2021). "Fourth, onset time of major endocrine ADRs (ICI-DM, adrenal insufficiency, hypophysitis/hypopituitarism, and thyroid dysfunction) differed between different ICI therapies, typically within 12 weeks in anti-CTLA-4 monotherapy but diffusely ranging from 0 to 48 weeks in anti-PD-1 monotherapy." (PMID 32507965, 2020). "The presence of hypophysitis secondary to a first ICPI (anti-CTLA-4, anti-PD-1 or anti-PD-L1) does not contraindicate the use of another ICPI." (PMID 30400055, 2019). "Our results and literature data definitely illustrate that hypophysitis can occur regardless of the ICI target (CTLA4, PD1 or PD-L1) and its indication." (PMID 31857638, 2019). "In contrast to previous studies, we found an increased incidence of hypophysitis with anti‐PD1/anti‐PDL1 and a rarity of primary thyroid dysfunction with anti‐CTLA4 treatment, which could be attributed to genetic/ethnic variations." (PMID 31518074, 2019). "Pituitary autoantibodies were detected in patients who developed hypophysitis following treatment with Ipilimumab (a monoclonal antibody targeting CTLA-4), but these antibodies were not present in patients without hypophysitis." (PMID 28702249, 2016). "This has not been consistently demonstrated with anti-CTLA-4 hypophysitis as many if not most of these patients will not have a biopsy performed." (PMID 25694832, 2015). "Moreover, in an autopsy series of six cancer patients treated with CTLA-4 blockade, one had clinical and pathologic evidence of hypophysitis, while a second one had mild lymphocytic infiltration in the pituitary gland without clinical signs of hypophysitis." (PMID 41002414, 2025). "Furthermore, recent evidence suggests that the occurrence of anti-CTLA-4 induced hypophysitis may be independent of the dose (10 versus 3 mg/kg) and the number of treatment cycles." (PMID 36983597, 2023). "Although anti-pituitary antibodies were present in patients with ipilimumab-related hypophysitis, the involvement of ADCC and complement activation has not been clarified in anti-CTLA-4-induced hypophysitis in humans." (PMID 38910605, 2024).
hypophysitis (continued). "The putative antigens of immunotherapy-induced hypophysitis and hypopituitarism were not completely clarified, despite preliminary studies suggesting ACTH, prolactin, and CTLA-4 as possible disease antigens." (PMID 34683167, 2021). "There is no consensus on whether IAD by ICIs can be classified as hypophysitis, whereas ACTH is more commonly affected than thyrotrophs and gonadotrophs in anti-CTLA4-induced hypophysitis." (PMID 37415148, 2023). "In contrast, CTLA-4 monotherapy rarely precipitates diabetes, potentially reflecting both narrower clinical utilization and the constitutive expression of CTLA-4 in pituitary tissue, which may bias toxicity toward hypophysitis rather than pancreatic autoimmunity." (PMID 41607457, 2026).
colorectal cancer (184 papers, 2011 to 2026). A primary or metastatic malignant neoplasm that affects the colon or rectum. "In a separate large case-control study conducted in China, SNPs in the CTLA-4 immune checkpoint pathway were examined in relation to colorectal cancer risk and survival." (PMID 41244914, 2025). "High expression of ICOS RNA was associated with high PD-1, high PD-L1, high CTLA-4, and non-colorectal cancers." (PMID 40297627, 2025). "In colorectal cancer, the expression of PD-1 and CTLA-4 on T cells and regulatory T cells is associated with a poor prognosis." (PMID 38415252, 2024). "Other authors have found a strong linkage between CTLA-4 genetic variants and some malignant tumors, like osteosarcoma, gastric and colorectal cancers, cervical squamous cell carcinoma, and thyroid cancer." (PMID 39194710, 2024). "In conclusion, this is the first study to evaluate the role of CTLA-4 polymorphisms in the risk of developing colorectal cancer in the Saudi population." (PMID 37107632, 2023). "As colorectal cancer is one of the most common cause of liver secondary tumors, cytotoxic T lymphocyte antigen-4 (CTLA-4) is an inhibitory immune checkpoint that can be expressed in tumor-infiltrating lymphocytes and colorectal cancer (CRC) cells." (PMID 36017002, 2022). "In fact, in a mouse colorectal cancer model, anti-CTLA-4 antibodies caused a rapid decrease of intratumoral Tregs, while they increased peripheral Treg cells." (PMID 35159059, 2022). "Although PD -1 or CTLA-4 monoclonal antibody may show some efficacy in colorectal cancer with DNA mismatch repair deficiency, more accurate biomarkers to predict immunotherapy effect remain to be found." (PMID 37287923, 2023). "Evidence from literature indicated the involvement of the CTLA-4 + 49 A/G variant in a number of diseases such as rheumatoid arthritis, Behcet’s disease, Graves’ disease, diabetes mellitus, thyroid diseases and colorectal cancer." (PMID 35525950, 2022). "Also, association of CTLA-4 gene polymorphisms were found in Japanese patients with rheumatoid arthritis, South Moroccan with type 1 diabetes, Chinese Han and Asian populations, and Iranian patients with gastric and colorectal cancers." (PMID 39854591, 2025). "Association of CTLA4 gene polymorphisms have been found in Japanese patients with rheumatoid arthritis, South-Moroccan patients with type 1 diabetes (T1D), Han-Chinese and Asian patients with breast cancer, as well as Iranian patients with gastric and colorectal cancers." (PMID 39854591, 2025). "MoST-CIRCUIT is the first trial that investigated combined anti-PD-1/CTLA-4 blockade in advanced dMMR/MSI-H non-colorectal cancers (CRC)." (PMID 41231502, 2026). "In preclinical models of lung and colorectal cancer, PC exhibited synergistic antitumor efficacy when combined with anti-cytotoxic T lymphocyte antigen 4 (anti-CTLA-4) antibodies." (PMID 41623165, 2026). "MoST-CIRCUIT is the first clinical trial to prospectively investigate immunotherapy using anti-PD-1/CTLA-4 blockade in patients with advanced dMMR/MSI-H non-colorectal cancers." (PMID 41231502, 2026). "Recently, the immunomodulatory effects of trogocytosis between cancer cell and immune cells were characterized through the transfer of TIM3 and CTLA4 from T cells to colorectal cancer cells and PD-1 transfer from leukemia cells to NK cells." (PMID 40183054, 2025). "Based on the results from the PICC and NICHE-2 studies, the CSCO Guidelines for Diagnosis and Treatment of Colorectal Cancer (2023) recommends the use of ICIs (PD-1 ± CTLA-4) for dMMR/MSI-H patients at cT4b, followed by radical surgery." (PMID 41561746, 2025). "Recent research suggests that CTLA4 in combination with some shRNAs (sh-circQSOX1) can effectively reduce the resistance of colorectal cancer immunotherapy." (PMID 40308511, 2025).
colorectal cancer (continued). "Our goal in this work was to develop a formula that targets the PD1/ PDL1, and CTLA-4 genes in colorectal cancer in vitro using super-paramagnetic @Silver @Chitosan nanoparticles (SPION@Ag@CS) loaded with mir-497-5p." (PMID 39905036, 2025). "Immune checkpoint inhibition (PD-1 ± CTLA-4) with anti-EGFR demonstrated activity in previously treated colorectal cancer in two prior studies, with ORR 8% to 35% and median PFS 3.6 to 5.7 months." (PMID 41171165, 2025). "Anti-CTLA-4 antibodies, especially in combination with other immunotherapies like anti-PD-1/PD-L1, have shown promising results in colorectal cancers with MSI-high (MSI-H)." (PMID 41035646, 2025). "In vitro and in vivo colorectal cancer organoid models demonstrated trogocytic interactions between tumor and immune cells, resulting in the acquisition of immunoregulatory proteins CTLA4, VISTA, TIM3, CD38, and CD80." (PMID 40183054, 2025). "Dual CTLA4/PD-1 blockade therapy achieves an objective response rate of 55% in dMMR colorectal cancer patients." (PMID 41415289, 2025). "In colorectal cancer mice, L. johnsonii combined with CTLA-4 inhibitors reduced tumor volume by 85% compared to CTLA-4 inhibitors alone." (PMID 40621452, 2025). "In one study, exosomes loaded with PD-L1, and CTLA-4 siRNAs were shown to knock down PD-L1 and CTLA4 gene expression, inhibiting colorectal cancer cell proliferation and tumor growth in vivo." (PMID 39355533, 2024). "Anti-PD-1, anti-PD-L1, and anti-CTLA-4 are promising immune checkpoint blockers in colorectal cancer." (PMID 38415252, 2024). "Among the MSS colorectal cancers, tumors with ARID1A mutations showed higher expression of immune-related molecules (PD-1, cytotoxic T-lymphocyte antigen 4 (CTLA4)) and cytotoxic T cell infiltration compared to the ARID1A wild type." (PMID 38893118, 2024). "The engineered exosomes containing PD-L1, and CTLA-4 siRNA activated tumor immune response in vivo and repressed their immune escape of colorectal cancer cells." (PMID 39355533, 2024). "For example, in colorectal cancer, DNA hypomethylation and two repressive histone marks, H3K9me3 and H3K27me3, were shown to be involved in the upregulation of CTLA-4 and TIGIT genes." (PMID 39064019, 2024). "The efficacy and safety of PD-1/PD-L1 inhibitors combined with CTLA-4 inhibitors in the treatment of advanced colorectal cancer is controversial." (PMID 39555073, 2024). "For instance, in colorectal cancer, CircQSOX1 was found to activate glycolysis in colorectal cancer cells, fostering immune evasion and ultimately impeding the response to anti-CTLA-4 therapy in colorectal cancer patients." (PMID 38408962, 2024). "PD-1/PD-L1 inhibitors combined with CTLA-4 inhibitors have shown promising clinical responses in the treatment of colorectal cancer (CRC)." (PMID 39555073, 2024). "This meta-analysis aimed to evaluate the efficacy and safety of PD-1/PD-L1 inhibitors combined with CTLA-4 inhibitors for advanced colorectal cancer." (PMID 39555073, 2024). "In the MC38 mouse model of colorectal carcinoma, the anti-CTLA-4 VHH-VHHkappa conjugate eradicates tumors and reduces the number of intratumoral regulatory T cells." (PMID 39149504, 2024). "This has prompted the exploration of anti-CTLA-4 antibodies as immunomodulatory and immunotherapeutic strategies in colorectal carcinoma." (PMID 39355533, 2024). "This study needs to be evaluated in a larger Saudi population for prediction confirmation and exploring the beneficial role for CTLA-4 as a screening biomarker or immunotherapeutic agent against colorectal cancer." (PMID 37107632, 2023). "Nevertheless, investigating the expression and function of CTLA-4 in SW480 cells can provide valuable insights for evaluating the potential immunotherapies targeting CTLA-4, such as immune checkpoint inhibitors to colorectal cancer." (PMID 37370565, 2023).
colorectal cancer (continued). "Among these immune checkpoint genes, highly expressed CTLA4, LAG3 and TIGIT has been treated as diagnostic biomarkers for colorectal cancer." (PMID 37693891, 2023). "It was found that circQSOX1 upregulation in colorectal cancer inhibited the anti-CTLA-4 treatment response in colorectal cancer cells." (PMID 37781524, 2023). "This has led researchers to investigate the role of CTLA-4 in various cancers, including colorectal cancer." (PMID 37370565, 2023). "In this study, we sampled the repertoire over several time points following treatment with anti-CTLA-4, in a syngeniec mouse model for colorectal cancer, generating a longitudinal dataset of T cell clones and their abundance." (PMID 36823176, 2023). "Nowadays, PD-L1 inhibitors or combined CTLA4 inhibitors are the major strategies for advanced or metastatic MSI-H colorectal cancer, but some people still show drug resistance or progression." (PMID 37215717, 2023). "Our results revealed high expression of the CTLA-4 gene in colorectal cancer tissue as compared to normal tissue." (PMID 37107632, 2023). "This is the first meta-analysis to evaluate the efficacy and safety of immune checkpoint inhibitors, including PD-1, PD-L1, and CTLA-4 antibodies, as therapeutic options for colorectal cancer." (PMID 34716473, 2022). "In recent years, the main research hotspots for IRAEs for colorectal cancer include immune checkpoint inhibitors (PD-1, CTLA-4) and gut microbiota." (PMID 36387099, 2022). "Although there have been numerous attempts to target adaptive immune cells in colon cancer, both with anti-PD-1 and anti-CTLA-4 immunotherapies, this has been unsuccessful in >80% of colorectal cancers." (PMID 36189323, 2022). "On one hand, Tregs cells exert greater immunosuppressive function by upregulating the expression of cytotoxic T lymphocyte antigen-4 (CTLA-4) and programmed death receptor-1 (PD-1) in colorectal cancer." (PMID 36199434, 2022). "Even if treatments with immune checkpoint inhibitors (anti-PD1, anti-PD-L1, anti-CTLA4) were proven effective for several cancer types, the benefit for colorectal cancer patients is still limited." (PMID 35207516, 2022). "Higher levels of IDO1 have also been detected in hypermutated colorectal cancers, suggesting a link with clinical benefit who receives anti-PD-1, anti-PD-L1, and anti-CTLA4 treatment." (PMID 35711437, 2022). "Genetic variants of IL-4 and CTLA-4 are reported to have association with several cancers including HCC, colorectal cancer, and head and neck cancer." (PMID 35525950, 2022). "In colorectal cancer mouse models, anti-CTLA-4 depletes intra-tumoral Tregs but enhances the proliferation and number of Tregs in the spleen, non-draining lymph nodes, and tumor-draining lymph nodes." (PMID 35326731, 2022). "In a colorectal cancer model, mice were treated with both anti-CTLA-4 and anti-PD-1 antibodies and imaged 1 hour post-injection of the tracer." (PMID 33391977, 2021). "Cytotoxic T lymphocyte antigen-4 (CTLA-4) is an inhibitory immune checkpoint that can be expressed in tumor-infiltrating lymphocytes and colorectal cancer (CRC) cells." (PMID 34067631, 2021). "PF06845102 has also been shown to potentiate anti-tumour activity of the anti-CTLA4 immune checkpoint inhibitor in a mouse model of colorectal cancer." (PMID 33708223, 2021). "A 89Zr-labeled anti-CD3 antibody was used to assess the immune-mediated response to CTLA-4 blockade, 3 days post-injection of the tracer in a preclinical colorectal cancer model." (PMID 33391977, 2021). "In this report, we present a case of irAEs in a patient treated for colorectal cancer with combination therapy with ipilimumab (anti-CTLA-4 antibody) and nivolumab (anti-PD-1 antibody)." (PMID 34430146, 2021). "Concordant to this, previous research on colorectal cancer found immune checkpoint expression of PD-1, PD-L1, CTLA-4, LAG-3, and IDO as a counterbalancing part of highly inflamed tumors (MSI unstable)." (PMID 33029538, 2020).